JAG1 (jagged canonical Notch ligand 1)
Diseases named in the same sentence as JAG1 in open-access papers (continued):
Sharing a sentence is not in itself a finding about the gene and the disease.
craniosynostosis (4 papers, 2022 to 2025). Craniosynostosis is defined as the premature fusion of one or more cranial sutures leading to secondary distortion of skull shape resulting in skull deformities with a variable presentation. "While our functional studies focused on genes uniquely associated with variation in skull BMD, there are plenty of genes implicated in craniosynostosis (e.g., EN1, RUNX2, SOX6, BMP2, JAG1, LRP5, IDUA30,44,47,48) across the whole set of identified BMD loci." (PMID 37402774, 2023).
endometriosis (4 papers, 2013 to 2023). The growth of functional endometrial tissue in anatomic sites outside the uterine body. "Inconsistently, the current study demonstrated that NOTCH1, JAG-1, JAG-2, and survivin, as a down target molecule of NOTCH pathway, significantly decrease in women with PCOS, endometriosis, and RIF." (PMID 31168348, 2019). "Western blot analysis showed a significantly lower JAG1 and JAG2 protein expression in the endometrial samples of PCOS patients, and endometriosis and RIF groups compared with the healthy fertile ones." (PMID 31168348, 2019). "A significantly lower expression of JAG1 was observed in PCOS (P<0.0001), endometriosis (P<0.001), and RIF (P<0.001) groups compared with the healthy fertile women." (PMID 31168348, 2019). "In a recent study involving women with endometrial disorders including RIF, endometriosis, and PCOS, the expression pattern of NOTCH pathway molecules including NOTCH1, 3, JAG1, 2, and survivin in the mid-luteal phase were distinctly expressed in the patient groups compared to controls." (PMID 36776897, 2023). "The expression of JAG1 was increased from proliferative into secretory phase, which proposes a responsibility for JAG1 in the endometrial receptivity, and the endometrial expression of JAG2 was decreased in endometriosis, which is contributed to the decidualization failure." (PMID 31168348, 2019).
Hypertension (4 papers, 2012 to 2022). The presence of chronic increased pressure in the systemic arterial system. "Using a systematic review and Jag1Ndr/Ndr mice, we identified female sex, hypertension, reduced skull thickness, premature vascular aging, and increased venous tortuosity as risk factors negatively impacting JAG1‐deficient vasculature." (PMID 36345711, 2022). "We also found GML-CYP11B1 rs3819496, MYL2-CUX2 rs12229654, and JAG1 rs1887320 to be significantly associated with decreased risk of hypertension in participants with sodium intake ≥2 g/day." (PMID 32854392, 2020). "Association of JAG1 rs1887320 with hypertension and CVD risk was reported in Chinese cohorts." (PMID 32854392, 2020). "Mechanisms underlying the association between JAG1 genotype and systemic hypertension might parallel those observed in pulmonary hypertension, but experimental data for this hypothesis are lacking." (PMID 31686456, 2019). "Previously, several GWASs reported links between JAG1 genotype and increased SBP and DBP, and higher odds of hypertension and coronary artery disease in the general population." (PMID 31686456, 2019).
Jaundice (4 papers, 2017 to 2024). Yellow pigmentation of the skin due to bilirubin, which in turn is the result of increased bilirubin concentration in the bloodstream. "Double heterozygous mice of Jag1 and Notch2 display jaundice associated with defects in bile duct epithelial cell differentiation and morphogenesis." (PMID 29142904, 2017).
keloid (4 papers, 2021 to 2023). An irregularly shaped, elevated mark on the skin caused by deposits of excessive amounts of collagen during wound healing. "Through immunohistochemistry staining, we found that the expression of DKK1 and PTN was lower in the keloid, while JAG1 and LGR5 showed a higher expression in the keloid." (PMID 35967426, 2022). "In the GSE7890 dataset, DKK1 and PTN were downregulated in keloid, whereas JAG1 and LGR5 were upregulated in keloid." (PMID 35967426, 2022). "In conclusion, we identified four immune signaling molecules associated with keloid (LGR5, PTN, JAG1, and DKK1)." (PMID 35967426, 2022). "It was found that JAG1 was significantly overexpressed at the mRNA and protein levels in keloid as well as in immune cells." (PMID 35967426, 2022). "JAG1 participates in the regulation of homeostasis in human tissues and plays an important role in the proliferation, migration, and invasion of fibroblasts, which can lead to changes in Notch receptor expression in keloid." (PMID 35967426, 2022). "We found that the expression of DKK1 and PTN was downregulated, while the expression of JAG1 and LGR5 was upregulated in keloid." (PMID 35967426, 2022). "We also found significantly increased NOTCH signaling, such as JAG1-NOTCH1, in keloid." (PMID 34140509, 2021). "Finally, four genes related to keloid (LGR5, PTN, JAG1, and DKK1) were identified, and we further studied keloid pathogenesis, which may provide new ideas and insights for keloid treatment." (PMID 35967426, 2022).
leprosy (4 papers, 2016 to 2022). Leprosy is a chronic infectious disease affecting primarily the skin and peripheral nervous system. "A potential regulating factor in leprosy as it pertains to macrophage polarity is the protein jagged 1 (JAG1)." (PMID 36326715, 2022). "NOCTH1 is known to be activated by JAG1 on endothelial cells, regulating the differentiation of M1 macrophages in PB leprosy." (PMID 29593724, 2018). "JAG1 expression in leprosy lesions was validated by immunohistochemistry, which demonstrated that JAG1 was expressed within the dermis and the granulomas in T-lep, but not L-lep lesions." (PMID 27532668, 2016). "Together, these data indicated that JAG1 expression correlated with M1 MΦ accumulation at the site of disease in leprosy." (PMID 27532668, 2016). "By studying leprosy as a model, we provide evidence that upregulation of JAG1 on endothelium instructs monocytes to differentiate into M1 MΦ with antimicrobial activity." (PMID 27532668, 2016). "In the self-limited form of leprosy, JAG1 expression is restricted to microanatomical regions of the granuloma enriched for M1 MΦ." (PMID 27532668, 2016). "JAG1 protein was preferentially expressed in the lesions from the self-limited form of leprosy, and localized to the vascular endothelium." (PMID 27532668, 2016). "Furthermore, NOTCH1/2 are expressed on activated Th1 cells and are critical to the protective response against Leishmania major infection by the production of IFN-γ, which is also important for leprosy protection by JAG1 stimulation." (PMID 29593724, 2018). "The presence of IFN-γ, JAG1-expressing EC and CD209+CD163neg MΦ in the self-limited form of leprosy suggests that the IFN-γ-JAG1-antimicrobial MΦ differentiation pathway contributes to host defense at the site of disease in leprosy." (PMID 27532668, 2016).
non-small cell lung carcinoma (4 papers, 2016 to 2022). A group of at least three distinct histological types of lung cancer, including non-small cell squamous cell carcinoma, adenocarcinoma, and large cell carcinoma. "High expression of JAG1 has been associated with increased migration and invasion of tumor cells and metastasis and poor prognosis in non-small cell lung cancer (NSCLC)." (PMID 30231940, 2018). "In non-small cell lung cancer, JAG1 has been identified in a nine gene-signatures which can possibly be used as genetic markers." (PMID 26930648, 2016). "However, the functionality of JAG1 in non-small cell lung cancer (NSCLC) has not been investigated thoroughly." (PMID 26930648, 2016).
pancreatic ductal adenocarcinoma (4 papers, 2017 to 2025). An infiltrating adenocarcinoma that arises from the epithelial cells of the pancreas. "For example, high Jag1 expression plays an important role in mediating plasticity and tumor heterogeneity in pancreatic ductal adenocarcinoma cells." (PMID 41315239, 2025). "A significant correlation between YAP and Jag-1 staining was observed in pancreatic ductal adenocarcinoma (r = 0.442, p < 0.001)." (PMID 29383103, 2017).
pulmonary stenosis (4 papers, 2019 to 2024). "Mutations in JAG1 also contribute to heart diseases such as tetralogy of Fallot (TOF), pulmonary stenosis, and patent ductus arteriosus." (PMID 37781534, 2023). "Jag1 and Notch2 double heterozygous mice exhibit RV hypoplasia, pulmonary stenosis, VSD, and ASD54." (PMID 39085358, 2024). "A 2010 study screened a cohort with right-sided cardiac defects for JAG1 mutations and found functionally significant sequence variants in 3% of the TOF cases and 4% of the pulmonic stenosis/peripheral pulmonary stenosis/pulmonary valve atresia with intact ventricular septum cases." (PMID 37781534, 2023). "Both Alagille Syndrome 1 ALGS1 (MIM:118450) and Right Atrial Isomerism RAI (MIM:208530) not only share phenotypic similarities with TOF such as pulmonary stenosis (ALGS1) and complete atrioventricular septal defects (RAI), but also have disease genes in common with TOF, namely JAG1 and GDF1." (PMID 38200084, 2024).
acute myeloid leukemia (3 papers, 2012 to 2022). Acute myeloid leukemia (AML) is a group of neoplasms arising from precursor cells committed to the myeloid cell-line differentiation. "In contrast, JAG1 has been deemed a tumor suppressor gene in acute myeloid leukemia, which cancer cell growth can be reduced and patients with JAG1 overexpression also have a better prognosis." (PMID 36071128, 2022).
ameloblastoma (3 papers, 2019 to 2024). The most common odontogenic tumor, arising from the epithelial component of the embryonic tooth and usually affecting the molar-ramus region of the mandible or maxilla. "Some studies have reported the expression of NOTCH1, 2, and 3, as well as their ligands DLL1, DLL4, and JAG1, in all ameloblastomas analyzed." (PMID 32155948, 2020). "Expression of NOTCH2 and NOTCH3 was associated with expression of the ligands JAG1, DLL1, and DLL4 in the ameloblastoma epithelium." (PMID 32155948, 2020). "We observed that NOTCH3, JAG1, DLL1, and DLL4 are also expressed within the ameloblastoma tumor mass." (PMID 32155948, 2020).
cardiac hypertrophy (3 papers, 2018 to 2022). "MicroRNA-21 (miR-21), transforming growth factor beta-1 (TGFβ-1), and Jagged1 (JAG1) were evaluated to determine whether conditions of cardiac hypertrophy and the MTS system can mediate gene expression in cardiac fibroblasts." (PMID 32867131, 2020).
Cerebral ischemia (3 papers, 2013 to 2022). Restriction of arterial blood supply to the brain associated with insufficient oxygenation to support the metabolic requirements of the tissue. "In the case of cerebral ischemia, the level of miR‐124 is reduced in the SVZ, and this reduction inhibits neuronal progenitor cell proliferation because jagged‐1 (JAG1) expression is repressed." (PMID 35481944, 2022).
coronary artery disease (3 papers, 2019 to 2022). "High level of miR-34a was related to coronary artery disease independently [OR [95% CI: 3.87 (1.56-9.56)]; P = 0.003] and the increased level was associated with expression of SIRT1, JAG1,CTNNB1, ATF1, and Notch2 inversely." (PMID 35155600, 2021).
cyst (3 papers, 2018 to 2025). A sac-like closed membranous structure that may be empty or contain fluid or amorphous material. "JAG1, a oocyte secreting protein, promotes cyst breakdown via activating Notch signalling in granulosa cells." (PMID 39833146, 2025).
Duchenne muscular dystrophy (3 papers, 2016 to 2024). Duchenne muscular dystrophy (DMD) is a neuromuscular disease characterized by rapidly progressive muscle weakness and wasting due to degeneration of skeletal, smooth and cardiac muscle. "Among this cohort of miRNAs, studies have illuminated the role of miR-199a-5p in Duchenne muscular dystrophy (DMD), where it influences the WNT signaling pathway via genes such as FZD4, JAG1, and WNT2, thereby impacting cellular proliferation and myogenic differentiation." (PMID 38600177, 2024).
lung adenocarcinoma (3 papers, 2019 to 2023). A carcinoma that arises from the lung and is characterized by the presence of malignant glandular epithelial cells. "Our study revealed that angiogenic ability can stratify lung adenocarcinoma patients, and the population with higher JAG1 expression characterized by poor prognosis, low degree of T lymphocyte infiltration, high TGF-β response, and active metastasis-related EMT pathway." (PMID 36923423, 2023).
metastatic tumors (3 papers, 2012 to 2024). "The expression of JAG1 decreased, but DEG enrichment increased in metastatic tumors." (PMID 39074091, 2024).
migraine (3 papers, 2019 to 2023). "Our DEPICT gene analysis also prioritized JAG1 at the novel 20p12 migraine-associated locus." (PMID 34294844, 2021).
myocardial infarction (3 papers, 2019 to 2023). Gross necrosis of the myocardium, as a result of interruption of the blood supply to the area, as in coronary thrombosis. "The clinical roles of JAG1 can also extend to addressing cardiac conditions such as myocardial infarction and improving cardiac development." (PMID 37781534, 2023). "JAG1-NOTCH signaling is required for mesenchymal stem cell (MSC) differentiation into cardiomyocytes and cranial neural crest (CNC) cells differentiation into osteoblasts, making it a regenerative candidate for clinical therapy to treat craniofacial bone loss and myocardial infarction." (PMID 37781534, 2023).
osteoarthritis (3 papers, 2018 to 2024). A noninflammatory degenerative joint disease occurring chiefly in older persons, characterized by degeneration of the articular cartilage, hypertrophy of bone at the margins and changes in the synovial membrane. "Another group identified that ITCH alleviated LPS-mediated chondrocyte injury through regulating JAG1 ubiquitination in osteoarthritis." (PMID 37359559, 2023). "ITCH expression was decreased in osteoarthritis samples compared with normal cartilaginous samples, whereas JAG1 expression was elevated in osteoarthritis specimens." (PMID 37359559, 2023). "In conclusion, LPS-mediated chondrocyte injury and osteoarthritis-mediated articular cartilage damage were mitigated by ITCH in part via inhibition of Notch1 activation by enhancement of JAG1 ubiquitination and degradation." (PMID 37359559, 2023). "Here we undertook a study to determine if Notch inhibition by soluble Jagged1 (JAG1) peptides could be utilized to accelerate PMSC-induced cartilage regeneration in a mouse post-traumatic osteoarthritis (PTOA) model." (PMID 30242147, 2018). "More importantly, JAG1 treatment further enhanced this anti-apoptotic effect of PMSCs on cartilage, confirming that paracrine mechanisms are involved in the anti-osteoarthritis effect of PMSCs, and this effect could further be enhanced by the inhibition of Notch signaling via JAG1 treatment." (PMID 30242147, 2018). "Previous studies have demonstrated that the Notch ligand Jagged1 (JAG1) is abundantly expressed and markedly increased in cartilage from patients with osteoarthritis (OA), a disease characterized by destruction of articular cartilage due to progressive articular chondrocyte apoptosis." (PMID 30242147, 2018).
pituitary adenomas (3 papers, 2013 to 2020). "Furthermore, microarray analysis performed in the fractioned SP and main population from human GH and non functioning pituitary adenomas cells showed more than 1.5 fold increased expression of components of the Notch system in the SP, including HES1, JAG1 and NOTCH paralogs." (PMID 28915655, 2017).
prostate tumor (3 papers, 2015 to 2022). "In prostate tumors, JAG1 level is high within the prostate tumor-reactive stroma microenvironment that promotes angiogenesis, invasion, and tumorigenesis." (PMID 36428807, 2022). "Endothelial specific Jag1 over-expression TRAMP mice presented increased prostate weights relative to the respective controls (TRAMP Ctrl) at both early and late stages of prostate tumor development." (PMID 26213336, 2015). "As JAG1 and JICD expression levels are upregulated in 98% of prostate tumors, we investigated whether JAG1 regulated AR expression." (PMID 36428807, 2022).
Alzheimer disease (2 papers, 2017 to 2018). A progressive, neurodegenerative disease characterized by loss of function and death of nerve cells in several areas of the brain leading to loss of cognitive function such as memory and language. "Interestingly, JAG1 and, in a more general view, the Notch signaling pathway are important for the spatial memory and their expression is altered in the hippocampus of people suffering from Alzheimer's disease." (PMID 30214903, 2018).
anaplastic large cell lymphoma (2 papers, 2014 to 2018). Anaplastic large cell lymphoma (ALCL) is a rare and aggressive peripheral T-cell non-Hodgkin lymphoma, belonging to the group of CD30-positive lymphoproliferative disorders, which affects lymph nodes and extranodal sites. "Non-mutated Notch1 is highly expressed in Hodgkin lymphoma (HL) and anaplastic large cell lymphoma (ALCL) cells, and tumor-associated JAG1, overexpressed by bystander cells as well as by neighboring tumor cells, induces Notch1 activation and promotes tumor cell proliferation and survival." (PMID 25309874, 2014).
aneurysmal disease (2 papers, 2022 to 2025). "We here report two families with segregating JAG1 variants that present with isolated aneurysmal disease, as well as the first histological evaluation of aortic aneurysm tissue of a JAG1 variant carrier." (PMID 35819173, 2022).
auditory neuropathy (2 papers, 2022 to 2025). A hearing disorder characterized by impaired transmission of signals through the auditory nerve, resulting in mild to severe hearing loss and poor speech perception. "Here, we show that deletion of JAG1 in the cochlea results in hearing loss that resembles auditory neuropathy." (PMID 36400760, 2022). "Taken together, these results demonstrate that neonatal loss of JAG1 primarily affects the function of the inner hair cell pathway, resulting in a specific type of hearing loss that is clinically similar to auditory neuropathy." (PMID 36400760, 2022). "We found that deletion of Jag1 in neonatal supporting cells (Sox2CreER/+Jag1fl/fl) resulted in a specific form of hearing loss at 6 weeks that is clinically similar to auditory neuropathy." (PMID 36400760, 2022). "Specifically, we show that deletion of JAG1 during cochlear maturation disrupts the inner hair cell pathway and leads to a type of deafness clinically similar to auditory neuropathy." (PMID 36400760, 2022). "For instance, deletion of Jagged1 (JAG1), a Notch ligand, during cochlear maturation results in fused and elongated stereocilia, leading to auditory neuropathy-like hearing loss without affecting outer hair cells." (PMID 41463123, 2025).
Autoimmunity (2 papers, 2007 to 2017). The occurrence of an immune reaction against the organism's own cells or tissues. "Jag1 and Dll4 have opposite effects on sprouting angiogenesis and differential effects of Jag1 and Dll1,4 have been described on T cells proliferation and the regulation of T cell effector functions in autoimmunity." (PMID 28472949, 2017).
brain tumor (2 papers, 2020 to 2022). "This is true for Notch receptors and canonical Notch ligands such as Dll1 and Jag1 —some of the closest relatives to DLK1—and for proteins involved in brain tumor and neural stem cell maintenance like CD44 and p75NTR." (PMID 32205867, 2020).
cardiomyopathy (2 papers, 2019 to 2023). A disease of the heart muscle or myocardium proper. "Microvascular network growth and the angiogenic properties of the TAT in elderly patients with cardiomyopathy also seem to involve the upregulation of PDGFC, FGF2, NOTCH2, FOS, JAG1, and PDGFRA target genes." (PMID 37833902, 2023).
cervical tumor (2 papers, 2016 to 2018). "We validated the increased expression of JAG1 in Caski, as compared to C-33A cell lines, invasive cervical tumor-derived cell lines." (PMID 29921897, 2018).